ATP6V1E1 (ATPase H+ transporting V1 subunit E1)
Description:
Subunit of the V1 complex of vacuolar(H+)-ATPase (V-ATPase), a multisubunit enzyme composed of a peripheral complex (V1) that hydrolyzes ATP and a membrane integral complex (V0) that translocates protons. V-ATPase is responsible for acidifying and maintaining the pH of intracellular compartments and in some cell types, is targeted to the plasma membrane, where it promotes acidification of the extracellular environment. The V-ATPase complex also acts as an activator for mTORC1 on lysosomal membrane by promoting the guanine nucleotide exchange factor (GEF) of the Ragulator complex, thereby enabling mTORC1 recruitment.
Synonyms: p31; ATP6E; ATP6E2; Vma4; ARCL2C; ATP6V1E
Tractability: Small molecule: a structure with a bound ligand is known. Antibody: UniProt places it where antibodies can reach, with high confidence; its Gene Ontology location is reachable by antibodies, with medium confidence. PROTAC: ubiquitination databases record sites on it; its protein half-life has been measured.
Gene: Protein-coding gene on chromosome 22 (17,592,136 to 17,630,958, reverse strand). Ensembl gene ENSG00000131100.
Subcellular location: Apical cell membrane; Cytoplasmic vesicle, secretory vesicle, synaptic vesicle membrane; Cytoplasmic vesicle, clathrin-coated vesicle membrane; Lysosome membrane
Pathways (Reactome):
Transport of small molecules: Ion channel transport; Transferrin endocytosis and recycling
Cellular responses to stimuli: Amino acids regulate mTORC1
Developmental Biology: Regulation of MITF-M-dependent genes involved in lysosome biogenesis and autophagy
Immune System: ROS and RNS production in phagocytes
Signal Transduction: Insulin receptor recycling
Gene Ontology:
Molecular function: ATPase binding; guanyl nucleotide exchange factor activator activity; protein binding; proton-transporting ATPase activity, rotational mechanism
Biological process: cellular response to amino acid stimulus; positive regulation of TORC1 signaling; proton transmembrane transport; regulation of macroautophagy
Cellular component: apical plasma membrane; extracellular exosome; lysosomal membrane; lysosomal proton-transporting V-type ATPase complex; vacuolar proton-transporting V-type ATPase, V1 domain; cytosol; endosome; proton-transporting two-sector ATPase complex; clathrin-coated vesicle membrane; proton-transporting two-sector ATPase complex, catalytic domain; synaptic vesicle membrane
Genetic constraint (gnomAD): Loss-of-function variants: 17 observed, 29.92 expected, observed/expected ratio (o/e) 0.57, 90% interval 0.39 to 0.85. The upper end of that interval is the gene's LOEUF score, 0.85, which puts it in group 3 of 6, group 1 being the genes least tolerant of losing a copy. Missense variants: 146 observed, 241.61 expected, observed/expected ratio (o/e) 0.6, 90% interval 0.53 to 0.69. Synonymous variants: 75 observed, 77.64 expected, observed/expected ratio (o/e) 0.97, 90% interval 0.8 to 1.17.
Gene-disease validity (ClinGen):
ClinGen rates the evidence that ATP6V1E1 causes each of these diseases.
autosomal recessive cutis laxa type 2C (autosomal recessive): Limited.
Homologues: Orthologues: macaque ATP6V1E1 (100% identical), rabbit ATP6V1E1 (99% identical), mouse Atp6v1e1 (99% identical), guinea pig Atp6v1e1 (98% identical), rat Atp6v1e1 (96% identical), tropical clawed frog atp6v1e1 (85% identical), chimpanzee ATP6V1E1 (81% identical), zebrafish atp6v1e1b (78% identical), zebrafish atp6v1e1a (75% identical), Drosophila melanogaster Vha26 (63% identical), Caenorhabditis elegans vha-8 (58% identical). Paralogues in human: ATP6V1E2 (77% identical).
Diseases named in the same sentence as ATP6V1E1 in open-access papers:
ATP6V1E1 is named in the same sentence as 21 diseases in open-access papers, as found by Europe PMC text mining. Sharing a sentence is not in itself a finding about the gene and the disease. The quoted sentences say what the papers report.
cutis laxa (4 papers, 2020 to 2023). Cutis laxa (CL) is an inherited or acquired connective tissue disorder characterized by wrinkled, redundant and sagging inelastic skin associated with skeletal and developmental anomalies and, in some cases, with severe systemic involvement. "The mutant zebrafish models show morphological and functional features reminiscent of the phenotypic manifestations in cutis laxa patients carrying pathogenic variants in ATP6V1E1." (PMID 34143769, 2021).
osteosarcoma (2 papers, 2023 to 2024). A usually aggressive malignant bone-forming mesenchymal neoplasm, predominantly affecting adolescents and young adults. "In this study, a total of six key cuproptosis-mitochondrion genes (FDX1, TOMM20, NDUFB9, COX11, MFN2 and ATP6V1E1) associated with prognosis of osteosarcoma were finally identified." (PMID 37405988, 2023). "A total of six cuproptosis-mitochondrion genes (FDX1, COX11, MFN2, TOMM20, NDUFB9 and ATP6V1E1) were identified to be associated with the prognosis of osteosarcoma." (PMID 37405988, 2023). "The level of ATP6V1E1 mRNA is downregulated in osteosarcoma, and the ATP6V1E1 mRNA expression dysregulation leads to immune imbalance in osteosarcoma." (PMID 38800967, 2024). "Among them, FDX1, TOMM20 and NDUFB9 were associated with poor survival of osteosarcoma while COX11, MFN2 and ATP6V1E1 predicted good." (PMID 37405988, 2023). "The mRNA expression level of ATP6V1E1 was decreased in osteosarcoma." (PMID 37405988, 2023). "However, we are not aware of any study on the immunological aspects of FDX1, TOMM20, NDUFB9, COX11, MFN2 and ATP6V1E1 in osteosarcoma for the time being, which is a direction we need to study subsequently." (PMID 37405988, 2023). "Besides, the mRNA expression level of ATP6V1E1 was decreased in osteosarcoma." (PMID 37405988, 2023). "Compared with hFOB1.19, the mRNA expression of ATP6V1E1 was significantly down-regulated in MG63, U2OS and 143B osteosarcoma cells." (PMID 37405988, 2023).
autoimmune disease (1 paper, 2023). A disorder resulting from loss of function or tissue destruction of an organ or multiple organs, arising from humoral or cellular immune responses of the individual to their own tissue constituents. "Therefore, dysfunction of ATP6V1E1 may lead to dysregulation of immune responses, contributing to the development of various autoimmune diseases and cancer." (PMID 37405988, 2023).
congenital heart disease (1 paper, 2023). A heart disease that is present at birth. "Among these genes, amplification of the genes CECR2, SLC25A18 and ATP6V1E1, mapping within the critical region for CES, may be responsible for iris coloboma,congenital heart disease, craniofacial anomalies in patients with CES." (PMID 37880750, 2023).
glioma (1 paper, 2019). A benign or malignant brain and spinal cord tumor that arises from glial cells (astrocytes, oligodendrocytes, ependymal cells). "Out of the 13 signature genes, ATP6V1E1, EIF3D, ERCC1, GPNMB, MTDH, PCNA and NEDD9 have been reported to play crucial roles in various pathways and mechanism of glioma." (PMID 31632497, 2019).
lysosomal disorders (1 paper, 2023). "Here, we found that lysosomal channel proteins (ATP6V0B, ATP6V1E1, ATP6V0D1, ATP6V1F) were significantly decreased in AD, which may mediate the elevation of lysosomal pH leading to lysosomal disorders." (PMID 37334737, 2023).
Parkinson disease (1 paper, 2025). A progressive degenerative disorder of the central nervous system characterized by loss of dopamine producing neurons in the substantia nigra and the presence of Lewy bodies in the substantia nigra and locus coeruleus. "In contrast, the Amyg showed upregulation of genes linked to oxidative phosphorylation (Atp6v1e1, Atp5mc2, Atp6v0e2), Parkinson disease (Snca, Calm1, Slc39a10), and regulation of actin cytoskeleton (Arpc3, Nckap1, Cfl1), indicating increased mitochondrial metabolism and structural plasticity." (PMID 41394722, 2025).
cancer (5 papers, 2019 to 2025). A tumor composed of atypical neoplastic, often pleomorphic cells that invade other tissues. "For example, dysregulation of V‐ATPase activity, including the ATP6V1E1 subunit, is associated with cancer progression." (PMID 39294741, 2024). "MFN2 and ATP6V1E1 are two genes that associated with mitochondrial dynamics and metal ion transport, which were attribute to cancer development and chemoresistance." (PMID 37405988, 2023). "Notably, the upregulation of genes ATP6V1E1 and ATP6V1H associated with V-ATPase subunits facilitates ECM degradation and cancer cell invasion by acidifying the extracellular environment and activating matrix metalloproteinases." (PMID 40165955, 2025).
immune diseases (2 papers, 2020 to 2024). "In addition, genes related to immune diseases (e.g., BID, SMARCD3, ATP6V1E1, NFKB2), energy metabolism (e.g., HAO1, NDUFA7, CERS4, MTHFD1), and other factors were also screened." (PMID 38750582, 2024).
tumour (2 papers, 2024). "Gene Set Enrichment Analysis further implicated ATP6V1E1 in pathways related to tumour progression and immune suppression." (PMID 39294741, 2024). "The findings from this study elucidate the complex interplay between the tumour microenvironment and HCC progression, with a specific focus on the role of M2 macrophages and the molecular pathways influenced by ATP6V1E1." (PMID 39294741, 2024).
neurodegenerative disease (1 paper, 2024). A disorder of the central nervous system characterized by gradual and progressive loss of neural tissue and neurologic function. "Furthermore, alterations in ATP6V1E1 expression have been linked to neurodegenerative diseases, where impaired lysosomal function leads to the accumulation of toxic proteins and cellular debris." (PMID 39294741, 2024).
ATP6V1E1 also shares sentences with these, for which no sentence is quoted: cat-eye syndrome (2 papers); hair loss (1); heart disease (1); hepatocellular carcinoma (1); Immunodeficiency (1); iris coloboma (1); liver disease (1); malignant glioma (1); rheumatoid arthritis (1); sensorineural deafness (1).